RN7SL48P (RNA, 7SL, cytoplasmic 48, pseudogene)
Gene: Miscellaneous RNA gene on chromosome X (18,915,243 to 18,915,535, reverse strand). Ensembl gene ENSG00000266710.
Homologues: Orthologues: chimpanzee Metazoa_SRP (98% identical). Paralogues in human: Metazoa_SRP (75% identical), RN7SL377P (73% identical), Metazoa_SRP (70% identical), RN7SL279P (70% identical), RN7SL202P (69% identical), RN7SL32P (69% identical), RN7SL155P (69% identical), RN7SL275P (69% identical), Metazoa_SRP (68% identical), RN7SL716P (68% identical), RN7SL850P (68% identical), Metazoa_SRP (67% identical), and 702 more.